IL1B (interleukin 1 beta)
Diseases named in the same sentence as IL1B in open-access papers (continued):
Sharing a sentence is not in itself a finding about the gene and the disease.
infection (continued). "Additional analysis of several cytokines (Tnf-α, Il-6, IL-1β, and IFN-γ) and antimicrobial factors (Reg3γ, S100a8, and S100a9) found to increase during RIMD infection showed a similar trend, i.e., they were also strongly induced by infection with POR1 or POR2 but not POR3." (PMID 31848276, 2019). "Importantly, those that received Eritoran treatment after PR8 infection but prior to Sp3 superinfection showed a significant decrease (P < 0.05) in both COX2 and IFN-β mRNA expression and a nonsignificant trend toward decreased IL-1β and TNF-α mRNA expression." (PMID 31064834, 2019). "Therefore, we quantified the production of cytokines produced by macrophages (IL-6, IL-10, TNFα, IFN-γ, GM-CSF and IL-1β□ in non-infected, Mtb-infection, HIV-infected and co-infected cultures over the course of an Mtb-infection using multiplex cytokine profiling." (PMID 31133636, 2019). "IL-1β levels were significantly increased in infected P2X4−/− compared to B6 BMDMs, but the absence of P2X4 did not reduce the amount of IL-1β released during nga(G330D) infections, suggesting that the NADase-dependent changes to IL-1β secretion are independent of this receptor." (PMID 31275321, 2019). "In addition, we showed that PAO1 infection of MPI cells, regardless of the strain, significantly induced the production (mRNA assessment) and release (protein measurement) of IL-1β and TNF-α." (PMID 30083156, 2018). "We demonstrate that, even without induced active infection, different baseline microbiota colonization patterns result in distinct inflammatory profiles in the brain as evidenced by the elevated expression levels of Nos1 in MPI-L mice and Il-1β and Tnf in GF mice." (PMID 29615691, 2018). "Similarly, in non-infected HIS-HUHEP mice, IL-1b, IL-12, IL-1Ra, IL-2R, CCL5, and IFN-γ, could be detected but did not significantly change post-infection." (PMID 28851562, 2017). "Interestingly, levels of IL-1β and IL-18 in the lung are markedly reduced in Nlrp3-/- mice with slower kinetics over the initial 6 days of infection with LVS or SchuS4 infection, but are not completely ablated." (PMID 27926940, 2016). "However, when we treated THP-1 monocytes, THP-1 derived macrophages, human primary monocytes and macrophages (either unprimed or LPS primed) with purified HCV virions at a multiplicity of infection (MOI) from 0.001 to 2 as indicated, no any IL-1β secretion was detected." (PMID 24400125, 2014). "This response was comparable to induction by type I IFN in the absence of infection, suggesting that despite the known ability of WNV to antagonize these responses, the synergy of IL-1β and type I IFN might act to overcome this antagonism and promote increased viral control." (PMID 23209411, 2012). "Infection with live CP, but not UVCP treatment, resulted in a significant decrease in ΔΨm as measured by a tetramethyl rhodamine methyl ester (TMRM) incorporation assay in BMDM, implicating a potential role of the mitochondria in NLRP3 inflammasome activation and IL-1β release." (PMID 21731762, 2011). "Differences in IL-1β responses could not be discerned in the Balb/cJ and C57BL/6J mice at these early times, likely due to the many genetic differences which could influence their cytokine response to infection." (PMID 21170303, 2010). "Interestingly, infection of PBMCs with MAB-S did not lead to high levels of IL-1β, although treatment of these infected cells with cysteamine and cystamine warranted a higher level of IL-1β in the supernatant compared to the untreated and amikacin-treated groups." (PMID 36674717, 2023). "Additionally, our findings regarding IFN-α, IL1β, IL8 and CSF2 are consistent with a previous gene expression study that demonstrated no significant upregulation of these innate markers in animals infected with PRRSV, regardless of whether the infection is persistent or non-persistent." (PMID 37409113, 2023).
tumor (3,805 papers, 1994 to 2026). "Conversely, genes associated with immune modulation and tumor progression such as IL-1β, inducible nitric oxide synthase (NOS2), cyclooxygenase (COX) 2, vascular endothelial growth factor (VEGF), and colony stimulating factor 1 (CSF-1) were upregulated." (PMID 41939865, 2026). "Interleukin (IL)-1β is a pro-inflammatory cytokine implicated in sterile inflammation and tumor development." (PMID 41977413, 2026). "Cytokines such as interleukin-6 (IL-6), tumor necrosis factor-alpha (TNF-α), IL-1β, and IL-8 are implicated in enhancing tumor growth, immune evasion, and metastasis." (PMID 41497141, 2026). "YWHAH emerged as a key TNF-associated, m6A-regulated gene, with elevated expression in naive/GC B cells, interleukin (IL)-1β+ tumor-associated macrophages, and differentiated epithelial cells." (PMID 41705255, 2026). "To assess the PCa tumour microenvironment for impaired immunity, we also performed a pilot RNA-expression analysis for PCa-associated immunological factors (IL1β, IL10, IL18, TNF-α, TLR4, GATA3, CD68)." (PMID 40430084, 2025). "For example, IL-1β, as a pro-inflammatory cytokine, is up-regulated in tumors such as breast cancer, promoting tumor growth and invasiveness, and is associated with poor prognosis." (PMID 39897552, 2025). "RNA sequencing results revealed significant differences in gene expression, with key genes (upregulated CXCR4, OPCML, and S100A2, and downregulated ATP1A3, CHL1, HLA-DRA, and IL-1β) associated with tumor invasiveness." (PMID 41374320, 2025). "Current research indicates that tumor-associated macrophages (TAMs) secrete various inflammatory cytokines, such as IL-1β, which facilitate the invasion of RCC by activating MMP-1 and other matrix metalloproteinases." (PMID 39976778, 2025). "Although encoded by separate genes, IL-1A and IL-1B exhibit identical biological functions, promoting inflammation and tumor progression." (PMID 40141426, 2025). "IL-1α and IL-1β also recruit and polarise tumour-associated macrophages and myeloid-derived suppressor cells, reinforcing an immunosuppressive microenvironment." (PMID 41465261, 2025). "By inhibiting IL-1β signaling, these inhibitors mitigate the immune suppressive environment that typically promotes M2 macrophage polarization, which is associated with tumor progression and immune evasion." (PMID 40109347, 2025). "In another study, Salmonella typhimurium, when intravenously injected into colon tumors, can increase necrosis factor alpha (TNF-α) and IL-1β expression, as well as the associated downstream signals, leading to anti-tumor effects." (PMID 39995663, 2025). "Ligands participating in these interactions are known immunosuppressive molecules (e.g., Tgfb1, Il1b), pro-angiogenic factors (e.g., Vegfa), or other genes associated with tumor progression (e.g., Fn1, Apoe, Apoc2)." (PMID 40216735, 2025). "Overexpression of TNF-α mRNA and IL-1β has been associated with increased tumor growth and invasion, both in epithelial and metastatic CRC." (PMID 41042771, 2025). "Nos2 has been demonstrated to promote NO synthesis, tumor death, and increasing pathogenic microorganisms, secreting a large number of pro-inflammatory factors, including IL-1β, C-X-C motif chemokine ligand 1 (CXCL1), and others." (PMID 40002899, 2025). "In parallel, monocytes and tumor-associated macrophages (TAMs) expressing markers such as Arg1, Spp1, and Il1b, are known to contribute immune suppression in PDAC and other malignancies." (PMID 40661354, 2025). "The induction of IL-1β production by macrophages is attributed to factors secreted by tumor cells, but here we show that compression alone, in the absence of any tumor-derived biochemical signals, causes an increase in Il1b gene expression." (PMID 41445746, 2025). "Interventions that reduce PGE2, inhibit NF-κB-driven cytokine programs, or limit NLRP3/IL-1β output can shift tumor-associated microglia/macrophages away from suppressive states." (PMID 41463173, 2025).
tumor (continued). "IL-1β is commonly recognized as a major tumor-promoting cytokine and his role is associated with unfavourable prognostic outcomes linked with cancer-related inflammation and compromised immune function." (PMID 41560727, 2025). "For NLRP12, it is shown to suppress colitis-associated colorectal cancer by limiting IL-1β production, while exist pro-tumor effects via NF-κB activation in prostate cancer." (PMID 40721869, 2025). "This IL-1β production, in turn, mediates the maturation, proliferation, and migration of tumor-associated macrophages (TAMs), ultimately promoting the growth and progression of PAAD tumors." (PMID 40386782, 2025). "In our study, we found that the environment of GBM cells exposed to MSCMel presented reduced levels of IFNγ, TNFα and IL-1β, and this condition was associated with a less aggressive tumor phenotype." (PMID 40083939, 2025). "Intriguingly, tumor-derived IL-1β has been implicated in enhancing local tumor control and improved patient survival, indicating a paradoxical role for the tumor inflammasome in tumor suppression." (PMID 40386782, 2025). "In contrast, the overexpression of Nrf2 and HO-1 in NSCLC cell lines, such as NCI-H292, SK-MES-1, and NCI-H460, promotes the expression of thymidine phosphorylase, IL-6, and IL-1β and subsequently facilitates tumor-associated angiogenesis." (PMID 40722961, 2025). "Tumor-associated macrophages in a murine model of Dalton’s lymphoma had increased IL-1β activity, measured as thymocyte proliferation, as compared to peritoneal macrophages in tumor-free animals." (PMID 39858071, 2025). "IL-6 and TNF-α are central activators of NF-κB, driving angiogenesis, epithelial–mesenchymal transition, and resistance to apoptosis, while IL-1β has been implicated in promoting immunosuppression and metastatic spread within the tumor microenvironment." (PMID 41020906, 2025). "Meanwhile, IL-1β is recognized for exacerbating colonic inflammation and supporting tumor microenvironment remodeling, mechanisms that are linked to the stimulation of the NLRP3 inflammasome." (PMID 41446797, 2025). "Noticeably, these effects are enhanced by IL-1β, a cytokine released by monocytes, macrophages, and neutrophils during chronic inflammation that is associated with bad prognosis and tumor progression in multiple solid tumors." (PMID 40725070, 2025). "Previous studies have highlighted IL-1β, IL-6, and IL-8 as key mediators of tumor-associated inflammation, with IL-1β expression correlating with disease progression and survival in molecularly defined NSCLC subgroups." (PMID 41303495, 2025). "In fact, AIM2, NLRP3 and RIG-1 were overexpressed in EBV-associated NPC and were interestingly reported to possess anti-tumour effects in EBV-associated NPC via IL-1β release." (PMID 41440367, 2025). "Beyond NSCLC, IL-1β has been implicated in breast, gastric, and colorectal cancers, where it contributes to tumor growth, metastasis, and therapy resistance." (PMID 40940992, 2025). "In the context of colitis-associated cancer (CAC), neutrophil-derived IL-1β stimulates intestinal mononuclear phagocytes (MPs) to produce IL-6, thereby promoting tumor growth." (PMID 41267807, 2025). "NLRP3 has been implicated in tumor myeloid cell infiltration due to its ability to promote IL-1β maturation through activation of caspase-1." (PMID 39273650, 2024). "The proinflammatory microglia produced high concentrations of nitric oxide (NO) and high levels of the proinflammatory cytokines TNF-α, IL-6, and IL-1β, and caused further DNA damage and promoted the apoptosis rate of tumor cells." (PMID 38750472, 2024). "Consistently, Il1b and Il1a expressions were significantly decreased in the tumor tissue of CCR2-deficient mice compared to WT mice, further corroborating that monocytes and monocyte-derived macrophages are the major source of IL-1 ligands in the colon TME." (PMID 39030280, 2024).
tumor (continued). "In liver cancer, tumor cells promote the recruitment and expansion of MDSCs within the TIME by releasing hypoxia-inducible factor 1-alpha (HIF-1α) and tumor-associated cytokines, such as IL-6, IL-1β, GM-CSF, G-CSF, VEGF, MCP-1, and MIF." (PMID 39596288, 2024). "Tumor-derived factors (i.e., IL-6, IL-10, IL-1β, PGE2, VEGF, GM-CSF, M-CSF, and IFN-γ) are implicated in the induction of MDSCs." (PMID 39272914, 2024). "The presence of IL1B in tumor cells correlated with a higher risk of relapse in both bone and other distant sites." (PMID 39125732, 2024). "IL-1β, known for inducing tumor angiogenesis and promoting immune evasion, was associated with worse outcomes, reinforcing its role as a negative prognostic factor." (PMID 39125732, 2024). "In the literature, the effect of a higher concentration of IL-1β is also associated with increased adhesion of monocytes to GBM tumor cells." (PMID 39399677, 2024). "Not only immune cells and fibroblasts, but also cancer cells are able to secrete interleukin-1β (IL-1β), which has been shown to be overexpressed in various solid tumors and linked to worse prognoses, promoting tumor growth and invasiveness." (PMID 39201656, 2024). "High tumor IL-1β expression was significantly associated with advanced tumor stage (Spearman’s rho = 0.226, p = 0.001)." (PMID 39801513, 2024). "We further evaluated the association of IL‐1β SNP with microvascular invasion and circulating tumor cells (CTCs) in peripheral blood to examine the impact of IL‐1β on hematogenous dissemination." (PMID 38798075, 2024). "We show that tumor-associated neutrophils not only respond to IL1β/CXCR2 in their environment but equally signal through IL1β and CXCR2 in an autocrine fashion." (PMID 38358352, 2024). "In RCC, IL-1β promotes the infiltration of myeloid-derived suppressor cells and tumor-associated macrophages and confers resistance to acquired and innate immunity." (PMID 38580797, 2024). "Conversely, increased abundance of lauric acid, IL-1β, and IL-2 in the Fit phenotype was observed, which have been previously implicated in tumor suppression and anti-tumor immunity." (PMID 39575261, 2024). "Stimulation of tumor‐associated macrophages to secrete IL‐1β and activation of tumor‐associated neutrophils contribute to metastatic progression and enhance systemic neutrophilic inflammation." (PMID 39317462, 2024). "TNF-α has tumor necrosis activity; IL-1β attracts neutrophils and causes the release of inflammatory mediators, which promotes the expression of vascular leukocyte adhesion molecules and induces inflammatory responses." (PMID 39063304, 2024). "This was supported by our results, where the stronger expression of AKT is associated with a worse tumor grade, through a correlation with IL-1β." (PMID 38397123, 2024). "These released growth factors promote the proliferation of cancer cells in the bone, further fuelling tumour growth which, in turn, produce more PTHrP, IL-1B and IL-6 to consequently cause a positive feedback loop." (PMID 38800348, 2024). "For example, IL1B + TAMs found in the hypoxic zone of pancreatic cancer are associated with poor tumor prognosis." (PMID 39068459, 2024). "Inflammasomes are activated in tumor cells, tumor-associated macrophages, tumor-associated fibroblasts, and bone-marrow-derived suppressive cells, resulting in the secretion of IL-1β and IL-18 in the TME." (PMID 38473997, 2024).
tumor (continued). "Mice lacking the inflammasome adaptor protein PYCARD (ASC) and caspase-1 also displayed higher tumor prevalence compared to wild-type mice, and the increased tumor burden was associated with reduced levels of IL-1β and IL-18 at the tumor site." (PMID 38553639, 2024). "The conditioned media from these cells had increased Wnt levels, promoting the expression of IL-1β by adjacent tumor-associated macrophages (TAMs), recruiting neutrophils, forming systemic inflammation, and promoting tumor metastasis." (PMID 39766882, 2024). "While our exploratory analysis found significant associations between IL-1B and IL-2 and lymphocyte infiltration, there is a need for additional mechanistic study to exploit the inflammatory axis to induce immune response to tumor." (PMID 38346068, 2024). "In the context of HNSCC, IL-1β was shown to be involved in several oncogenic mechanisms, such as the differentiation of tumor-associated macrophages which are associated with a poor prognosis." (PMID 39411143, 2024). "Conversely, increased IL-1β production is implicated in promoting tumour growth of breast cancer cells." (PMID 39516433, 2024). "We found that β-amyrin, lupeol, and quercetin inhibited the expression of IL-1β and IL-6, a result that is consistent with the point of view that inhibition of interleukin production also causes the inhibition of tumor cell growth." (PMID 39062057, 2024). "IL-1β derived from tumor-associated macrophages was also reported to promote tumorigenesis and blocking IL-1β led to tumor control." (PMID 38391959, 2024). "In a lung brain metastasis xenograft model, Nlrp3 and Il1b transcripts were upregulated in tumor-associated macrophages, suggesting possible inflammasome activation." (PMID 37749707, 2023). "Recent studies suggest that activation of the NLRP3 inflammasome and the resulting increase in IL-1β production are associated with tumor progression in various types of cancer, including LC." (PMID 36670473, 2023). "The cytokine interleukin 1β (IL-1β), produced by macrophages in the lung, is a mediator of cancer growth, metastasis, and tumor-associated macrophage infiltration." (PMID 37161053, 2023). "Mechanistically, HDM caused a particular subtype of CLI, in which the NLRP3/IL-1β signaling pathway is chronically activated in macrophages, and made the lung microenvironment conducive to tumor development." (PMID 36670473, 2023). "We further elucidate how these tumors activate NF-κB in tumor-associated macrophages in order to elicit the IL-1β they require for sustained growth." (PMID 36980752, 2023). "In this review, we will focus on the interactions between MCs, NK cells, and neuronal structure and their communications via proinflammatory cytokines, including TNFα, IL-1β, and IL-6, in peripheral neuropathy in association with tumor immunology." (PMID 37628724, 2023). "Though, tumor and tumor associated stromal cells secrete all these cytokines in a great extent, we found MDSCs are the major contributors in releasing IL-10, IL-6 and IL-1β over tumor cells itself." (PMID 38304256, 2023). "Next, to distinguish between prolonged survival reflecting Il1b loss in tumor versus TME cells, we orthotopically transplanted 30,000 cells from primary PDGFB mGBM (WT;Ntv-a mice) into the striatum of WT and Il1b–/– mice." (PMID 37733448, 2023). "Adipocyte-secreted IL-1β promoted obesity-induced pancreatic carcinogenesis and drug resistance by recruiting tumor-associated neutrophils in a mouse PDA model." (PMID 37081882, 2023). "Tumor-associated macrophages (TAMs) secrete high levels of IL-1β promoting endocrine resistance in HR+ BC." (PMID 37762557, 2023). "DEX caused a decrease in tumor size, tumor weight, and IL-1β and TNF-α levels and an increase in NK cell activity and IFN-γ level." (PMID 37528154, 2023).